ENSG00000281311
Gene: Small nucleolar RNA gene on chromosome 17 (64,146,337 to 64,146,471, forward strand). Ensembl gene ENSG00000281311.
Gene Ontology:
Biological process: RNA processing
Cellular component: nucleolus
Homologues: Orthologues: mouse Gm22711 (79% identical), mouse Gm23786 (69% identical), mouse Gm26047 (58% identical). Paralogues in human: SNORA50A (58% identical).